SPINK1 (serine peptidase inhibitor Kazal type 1)
Diseases named in the same sentence as SPINK1 in open-access papers (continued):
Sharing a sentence is not in itself a finding about the gene and the disease.
tumor (102 papers, 1986 to 2026). "We further conducted in vivo functional validation using murine xenograft models, demonstrating SPINK1`s causal role in tumor growth and metastasis—a critical advancement beyond correlative analyses." (PMID 40904507, 2025). "Mechanistically, SPINK1 has been implicated in tumor cell proliferation and metastasis through the MEK/ERK signaling pathway." (PMID 38540686, 2024). "In particular, SPINK1 (serine peptidase inhibitor Kazal type 1) was associated with survival and involved in the regulation of tumor sphere propagation, colony formation, invasion, and drug resistance." (PMID 39199659, 2024). "Lentivirus encoding Spink1 knockdown and chemotherapy combination produced a maximal suppression effect, as evidenced by reduced tumor size, suppressed liver weight and prolonged survival time." (PMID 38030644, 2023). "SPINK1 is strongly associated with aggressive cancer features and poor tumor differentiation in HCC as well as a more stem/progenitor and less differentiated state in liver development." (PMID 38030644, 2023). "We also elucidate a unique mechanism by which SPINK1 promotes chemoresistance in HCC through the induction of tumor plasticity, providing insights into the underlying processes of therapeutic response." (PMID 38030644, 2023). "Serine protease inhibitor Kazal type 1 (SPINK1) is also known as pancreatic secretory trypsin inhibitor (PSTI) or tumor-associated trypsin inhibitor (TATI)." (PMID 35194087, 2022). "Overexpression of SPINK1 has also been discovered in multiple tumors, including colon, lung, breast, and prostate, and is associated with tumor progression and poor prognosis." (PMID 33901011, 2021). "Accumulating evidence has shown that SPINK1 is associated with tumor malignant phenotypes, such as proliferation, angiogenesis, migration, invasion, metastases, and antiapoptosis." (PMID 34747365, 2021). "While the mechanism by which SPINK1 protects the pancreas is long established and well-understood, the mechanisms that underlie its tumor promoting properties are complex and multifaceted, with major questions remaining to be answered." (PMID 30778387, 2019). "SPINK1 has been considered a tumor-associated trypsin inhibitor, and overexpression of SPINK1 is a predictor of unfavorable outcomes in ovarian, prostate, liver, breast, and colon cancers." (PMID 31886233, 2019). "Altogether, the expression of key molecules associated with tumour-promoting pathways suggests enhanced malignancy driven by paracrine SPINK1 and indicates an adverse prognosis in the post-therapy stage." (PMID 30333494, 2018). "The use of tumor tissue RNA instead of DNA as the starting material enabled us to correlate the mRNA expression of BRAF V600E mutations directly with SPINK1 mRNA expression level analyzed by qPCR from the same tumor samples." (PMID 29193645, 2018). "In analysis of patients grouped by tumor stage (1/2 versus 3/4), SPINK1 expression in tumors was significantly associated with earlier stage (p = 0.007, Chi-square)." (PMID 26437224, 2015). "Similar to our results with the full cohort, we found that adjusting for stage and optimal debulking in nonserous subjects revealed yet stronger association between tumor SPINK1 expression and patient survival (HR 2.80, p = 0.0010)." (PMID 26437224, 2015). "A high level of SPINK1 expression has been reported to be associated with cancer progression, tumor recurrence and patient survival rates in certain other cancers, indicating that SPINK1 has additional functions in extrapancreatic cancers." (PMID 24932227, 2014). "In addition, ROC experiments validated the diagnostic significance of SPINK1 expression in distinguishing HCC specimens from non-tumor specimens with an area under the curve (AUC) greater than 0.70." (PMID 38093163, 2023). "The ssGSEA method was used to analyze the TCGA to determine whether there was an association between SPINK1 and tumor immune infiltrates." (PMID 38093163, 2023).
tumor (continued). "Next, we examined whether SPINK1 causes tumor radioresistance not only in vitro but also in vivo, using a xenografted tumor model." (PMID 34747365, 2021). "Similarly, in analysis of patients grouped by tumor grade (1 versus 2/3), SPINK1 expression in tumors was significantly associated with low grade (p < 0.0001, Chi-square)." (PMID 26437224, 2015). "However, the links between SPINK1 and autophagic process in cancer cell growth remain undiscovered, as well as the underlying molecular mechanisms with which SPINK1 may contribute to tumor development." (PMID 37305325, 2022). "These pathway-level changes were accompanied by reduced expression of transcripts frequently associated with tumor-promoting programs, such as SERPINA1, MDM2, PDGFA, TGFBR1/2, and SPINK1." (PMID 41596590, 2026). "Our findings highlight SPINK1 as a critical regulator of tumor progression and immune modulation, providing novel insights into OSCC pathogenesis and potential therapeutic strategies." (PMID 40904507, 2025). "CAS cells, predominantly found in tumour regions, expressed SPINK1, CEACAM6 and CEACAM5—genes implicated in tumour proliferation and migration in lung cancer." (PMID 40824728, 2025). "Functionally, the expression of SPINK1 is upregulated by inflammatory signals from the tumor microenvironment, particularly interleukin-6 (IL-6) Via the STAT3 pathway." (PMID 41465391, 2025). "Normal tissues exhibited higher levels of S100A9, FTCD, POF1B, IL7R, and MYO1E, whereas tumor tissues showed increased expressions of SPINK1, CXCL9, AGFG1, and IQGAP3." (PMID 41578779, 2025). "In cancer, SPINK1 overexpression is connected to tumor growth and therapeutic resistance, notably in HCC." (PMID 40872585, 2025). "Mechanistically, SPINK1 primarily mediates tumor progression through two pathways:As a member of the serine protease inhibitor family, SPINK1 disrupts the protease-antiprotease balance, leading to abnormal degradation of the extracellular matrix." (PMID 40904507, 2025). "Xenograft models demonstrated that SPINK1 knockdown markedly inhibited tumor growth, with a 50% reduction in tumor weight compared to controls at 21 days, underscoring its therapeutic potential." (PMID 40904507, 2025). "Previous studies showed that SPINK1 and trypsin are co-expressed in CRC, suggesting a potential protective role for SPINK1 against tumor invasion." (PMID 41465391, 2025). "Thor correctly localized PTPRC to immune areas and SPINK1 to the tumor boundary, aligning with pathology annotations." (PMID 40764306, 2025). "Their results reveal a novel connection between inflammatory signals from the tumor microenvironment and elevated SPINK1 levels." (PMID 41465391, 2025). "A decrease in SFTPA1 expression (an AT2 marker) was observed, whereas CEACAM6 and SPINK1 (CAS markers) exhibited high expression levels in tumour regions (GG and S) compared to the DN region." (PMID 40824728, 2025). "The M17 gene module comprises core genes including TIMP1, TFF2, ITM2A, SPINK1, and TSPAN8, intimately associated with tumor stemness maintenance and invasion-metastasis capacity." (PMID 41450464, 2025). "Volcano plots were utilized to visualize the expression patterns of these genes, revealing that genes such as GPC3 and SPINK1 were significantly upregulated in the tumor group, while genes including HAMP and CYP1A2 were markedly downregulated." (PMID 40864066, 2025). "the that correctly localized PTPRC to immune areas and SPINK1 to the tumor boundary, aligning with pathology annotations." (PMID 40162205, 2025). "The data obtained from the in vivo experiments demonstrated that SPINK1 overexpression significantly rescued tumor growth and promoted the occurrence of IHM and lung metastasis." (PMID 38693111, 2024). "Targeting the SASP components AREG or SPINK1 with specific antibodies enhanced the response to chemotherapy in tumor mouse models." (PMID 38195762, 2024).
tumor (continued). "There were 5 downregulated protein-coding gene identified in the positive margin group including SPINK1, a well-known tumor marker." (PMID 38038766, 2024). "To detect the protein expression level of SPINK1 in HCC patients, we searched SPINK1 protein expression levels in HCC cohort 1 and found higher SPINK1 protein levels in tumor samples than peritumoral normal tissues." (PMID 38540686, 2024). "Upon re-analysis of the tumor cell cluster in cohort 3, 39 sub-clusters were identified, among which SPINK1 showed variable expression levels." (PMID 38540686, 2024). "Emerging findings suggest that tumor cells secrete SPINK1, which regulates cancer proliferation, metastasis, drug resistance, transdifferentiation, and cancer stemness." (PMID 39687810, 2024). "The application of single cell RNA-sequencing (scRNA-seq) not only mitigated the confounding effects of tumor heterogeneities, but also facilitated the delineation of SPINK1 functions at the single cell level." (PMID 38540686, 2024). "Based on our research findings, we observed elevated SPINK1 expressions in HCC tissues when compared to non-tumor specimens." (PMID 38093163, 2023). "Functionally, SPINK1 overexpression promotes tumor initiation, self-renewal, and chemoresistance by driving a deregulated EGFR-ERK-CDK4/6-E2F2 signaling axis to induce dedifferentiation of HCC cells into their ancestral lineages." (PMID 38030644, 2023). "In the TCGA-LIHC dataset, SPINK1 was found to be frequently overexpressed in HCC compared to its non-tumor liver counterparts, and high SPINK1 was tightly correlated with worse overall survival." (PMID 38030644, 2023). "Of the 61 paired cases examined, 39 (63.9%) of them exhibited higher SPINK1 expression as compared to its adjacent non-tumor counterpart." (PMID 38030644, 2023). "We also show in a proof-of-concept model that endogenous depletion of hepatic SPINK1 in an immunocompetent HCC mouse model can impede tumor growth, and sensitize the tumor to chemotherapy." (PMID 38030644, 2023). "As compared with non-tumor specimens, we discovered that the level of expression of SPINK1 was much higher in HCC samples." (PMID 38093163, 2023). "It reveals a significant association between SPINK1 expression and the less differentiated HCC tumors, suggesting its potential as a biomarker for tumor aggressiveness." (PMID 38030644, 2023). "The amount of SPINK1 that was expressed in tumor tissue served as an independent predictor of overall survival." (PMID 38093163, 2023). "Addition of recombinant SPINK1 in MHCC97L cells promoted tumor-initiating ability and chemoresistance in vitro; while conversely, treatment of high-SPINK1 expressing Huh7 cells with a SPINK1 neutralizing antibody attenuated such events." (PMID 38030644, 2023). "Our current study identifies the involvement of the cell cycle regulatory pathway (ERK-CDK4/6-E2F2) in SPINK1-mediated tumor plasticity in HCC." (PMID 38030644, 2023). "Herein, we also explored if SPINK1 would act through EGFR to promote tumor-initiating and chemoresistance properties in HCC." (PMID 38030644, 2023). "We also interrogated publicly available datasets and tissue microarray to compare SPINK1 expression in non-tumor liver and HCC samples." (PMID 38030644, 2023). "Further analysis of human HCC data also found high SPINK1 expression to correlate with gene signatures relating to tumor recurrence, hepatic progenitor, poorly differentiated HCC and chemoresistance, but not cell cycle, G1 phase or G1/S transition." (PMID 38030644, 2023). "SPINK1 knockdown resulted in a 2-fold decrease in the ability of cells to self-renew, as demonstrated by decreased tumor-initiating frequency in vitro." (PMID 38030644, 2023). "A substantial correlation was found between higher SPINK1 expression in the tumor and the production of portal vein tumor thrombus as well as a shorter overall survival time." (PMID 38093163, 2023).
tumor (continued). "Our in vitro and in vivo experimental data convincingly demonstrated the role of SPINK1 in tumor growth, invasion, chemoresistance, anti-apoptosis, and metastasis and the favorable effect of the anti-SPINK1 antibody on the anti-proliferation of HCC cells." (PMID 35924241, 2022). "The tumor graft volume and the weight of SPINK1-OE H22 mice were significantly higher than those of the control (p < 0.01)." (PMID 35924241, 2022). "EGFR inhibitor significantly decreased tumor ability of proliferation, migration and invasion, rescued by upregulation of endogenous SPINK1." (PMID 36053457, 2022). "We did identify 1 ERG+ focus (0.1%) with simultaneous SPINK1 expression within the same tumor cells in less than 5% of the focus." (PMID 35050902, 2022). "More and more evidences show that SPINK1 is considered as a transforming factor in solid tumors and is involved in multiple stages of tumor progression, including invasion and metastasis." (PMID 35194087, 2022). "A significant increment in the tumor size, on average, was observed weekly, and this trend gradually reached the peak at 3 weeks after implantation of SPINK1-OE H22 tumor cells in mice." (PMID 35924241, 2022). "In subcluster 3, tumor cells from a recurrent patient displayed high expression levels of serine protease inhibitor Kazal-type 1 (SPINK1)." (PMID 35574365, 2022). "More importantly, SPINK1 has a profound effect on tumor cell proliferation, metastasis, drug resistance, stemness and differentiation." (PMID 35223512, 2022). "In the tumor microenvironment, SPINK1 promotes tumor growth and survival, and SPINK1 overexpression correlated to increased PCa aggressiveness and shortened PFS." (PMID 35205640, 2022). "Other genes identified included SPINK1, an inhibitor of apoptosis that has been associated with chemoresistance, and PARM1 which is an androgen-related gene that drives tumor proliferation." (PMID 35280731, 2022). "Of the 310 RP specimens (multifocal and unifocal) examined by dual ERG/SPINK1 IHC in all tumor foci, we identified collision tumors in 9.4% (n = 29) of patients." (PMID 35050902, 2022). "SPINK1 protein was detected in and around the hypoxic area of tumor tissue, and it increased with decreasing oxygen supply." (PMID 35223512, 2022). "IL-6 produced in ovarian clear cell carcinoma (OCCC) cells stimulates the common tumorigenic gene expression pattern by regulating the expression of SPINK1 to promote tumor peritoneal metastasis, anoikis resistance and proliferation." (PMID 35223512, 2022). "SPINK1 proteins were detected both within and around hypoxic regions of xenografted and clinical tumor tissues, and their plasma levels increased in response to decreased oxygen supply to xenografts." (PMID 34747365, 2021). "All the data indicate that SPINK1 can be utilized as a predictive plasma marker for the tumor hypoxic fraction and therapeutic effect of radiation." (PMID 34747365, 2021). "The most upregulated genes in PDAC include SPINK1, known for contributing towards increased tumor proliferation and poor cancer prognosis; TFF1, which facilitates PDAC metastasis; and S100A6, a key diagnostic marker for PDAC." (PMID 35178072, 2021). "SPINK1 modulated tumor malignancies and induced the activation of the downstream signaling of epidermal growth factor receptor (EGFR) in cancer cells, due to the structural similarity with epidermal growth factor (EGF)." (PMID 33916984, 2021). "We found that the expression of UGT2B4 was positively associated with expression of multiple well-known oncogenes such as SPINK1, IDH1, MYC, and SRC and negatively associated with expression of well-known tumor suppressors such as CIC and ERF." (PMID 33391440, 2021). "We then performed tumor growth delay assays using subcutaneous xenografted tumors grown from the stable transfectants and analyzed the effect of SPINK1 on tumor radioresistance in vivo." (PMID 34747365, 2021).
tumor (continued). "SPINK1 is also known to mediate the growth and differentiation of tumor via suppression of apoptotic pathway in cancer cells and protecting them from immune surveillance." (PMID 34469466, 2021). "Next, we addressed the molecular mechanism by which SPINK1 protected cancer cells from apoptotic cell death and enhanced tumor radioresistance." (PMID 34747365, 2021). "Based on the GSE14520 dataset, we found that the SPINK1 mRNA levels were significantly upregulated in tumor samples." (PMID 34595116, 2021). "The SPINK1 level was significantly higher in the tumor tissues (p < 0.001) and correlated with portal vein tumor thrombus formation (p < 0.019)." (PMID 33916984, 2021). "SPINK1 secreted from hypoxic cells induced cancer radioresistance in a paracrine manner and accelerated tumor growth after radiation therapy." (PMID 34747365, 2021). "In the present study, our focus is solely on providing the first in vitro and in vivo evidence supporting the utility of SPINK1 as a plasma biomarker for tumor hypoxia, and we will report the results of analysis with cancer patients in our next paper." (PMID 34747365, 2021). "Identification of SPINK1 as a candidate plasma marker for tumor hypoxia and therapeutic target for radiosensitization." (PMID 34747365, 2021). "Meanwhile, when the tumor xenografts were locally irradiated with γ-rays at a dose of 10 Gy, the SPINK1 overexpression enhanced tumor growth after the radiation treatment." (PMID 34747365, 2021). "All of these in vitro and in vivo data clearly suggest that SPINK1 protein secreted from hypoxic tumor cells induced tumor radioresistance in a paracrine manner and accelerates tumor growth after radiation therapy." (PMID 34747365, 2021). "This is consistent with previous studies demonstrating higher levels of SPINK1 in normal pancreatic tissue compared to tumor." (PMID 32195182, 2020). "In this study, we observed that levels of SPINK1 (Uniprot: ISK1_Human) were decreased in tumor tissue compared to adjacent normal pancreas." (PMID 32195182, 2020). "SPINK1 has also been reported to confer apoptotic resistance on tumor cells in the context of chemotherapeutic treatment." (PMID 30778387, 2019). "The identification of specific protease targets of SPINK1 inhibition will reveal pathways controlling anoikis resistance and aid in development of biomarkers and therapeutic strategies to reduce tumor metastasis." (PMID 30778387, 2019). "Studies in experimental model systems have demonstrated significant effects of SPINK1 in promoting tumor cell growth and survival, the mechanisms of which remain to be fully elucidated." (PMID 30778387, 2019). "In other tumor types, multiple studies have explored the potential utility of SPINK1 expression as a biomarker through analysis of tumor tissues, urine, and serum." (PMID 30778387, 2019). "A second important mechanism by which SPINK1 influences tumor progression is its ability to stimulate tumor cell proliferation." (PMID 30778387, 2019). "To better understand and target SPINK1 driven tumor cell proliferation we need to further investigate the missing link between SPINK1 and EGFR signaling using modern methods and technologies." (PMID 30778387, 2019). "In contrast to cetuximab, however, SPINK1 mAb generated significantly, albeit slightly more apoptotic cells in tumours." (PMID 30333494, 2018). "Our findings establish SPINK1 as both a tumour-promoting factor that is targetable to prevent disease exacerbation and an important biomarker to monitor the TME response to anticancer agents in clinical settings." (PMID 30333494, 2018). "To investigate the mechanism directly responsible for SPINK1-induced cancer resistance, we dissected tumours from animals treated by different agents 7 days after treatment, a time point prior to the development of resistant colonies." (PMID 30333494, 2018). "Conversely, knockdown of SPINK1 from PSC27SPINK1 cells prior to tumour implantation resulted in considerably reduced tumour volumes." (PMID 30333494, 2018).